MUL1 (mitochondrial E3 ubiquitin protein ligase 1)
Diseases named in the same sentence as MUL1 in open-access papers (continued):
Sharing a sentence is not in itself a finding about the gene and the disease.
Obesity (1 paper, 2024). Accumulation of substantial excess body fat. "It proposes MUL1 as a promising target for the development of chemical inhibitors or therapeutic siRNAs to combat obesity and associated metabolic diseases." (PMID 38725872, 2024). "Overall, our studies implicate MUL1 as a promising therapeutic target for the development of interventions aimed at combating obesity and associated metabolic diseases." (PMID 38725872, 2024). "On the contrary, Mul1(−/−) animals showed resistance to HFD-induced obesity with very little increase in body weight (p < 0.05 for the first 10 weeks or p < 0.01 from week 10–16)." (PMID 38725872, 2024). "Our studies suggest that the induction of MUL1 protein during conditions of nutritional overload is necessary, and essential for fat accumulation and the obesity that follows in mice." (PMID 38725872, 2024). "In our present study, we investigate the role of MUL1 in obesity and mitochondrial metabolism using mice with a whole-body inactivation of the Mul1 gene (Mul1(−/−))." (PMID 38725872, 2024). "The absence of MUL1 expression in Mul1(−/−) mice on HFD causes increased metabolic rate, reduced lipogenesis, and robust resistance to obesity." (PMID 38725872, 2024). "In the present study, we used mice with whole-body Mul1 inactivation, to investigate the function of this ubiquitin ligase in mitophagy and the regulation of lipid metabolism and obesity." (PMID 38725872, 2024). "Following 16 weeks of HFD, wild-type, Mul1(+/+) animals, exhibited all the symptoms of HFD-induced obesity including a significant increase in body weight." (PMID 38725872, 2024). "Several metabolic and lipidomic pathways are perturbed in the liver and white adipose tissue (WAT) of Mul1(−/−) animals on HFD, including the one driven by Stearoyl-CoA Desaturase 1 (SCD1), a pivotal regulator of lipid metabolism and obesity." (PMID 38725872, 2024).
prion disease (1 paper, 2024). A transmissible disease that is caused by a protein that is able to induce abnormal folding of normal cellular proteins, leading to characteristic spongiform brain changes, which are associated with neuronal loss without an inflammatory response. "Since our data suggest that PINK1/Parkin mediated mitophagy is protective during prion infection, it’s possible that prion disease would progress even faster if mice were ablated for MUL1 or Nix, in addition to PINK1 or Parkin." (PMID 38394123, 2024).
renal carcinoma (1 paper, 2022). A carcinoma arising from the epithelium of the renal parenchyma or the renal pelvis. "JADE1 for example, has been shown to promote apoptosis in renal cancer cells, and MUL1, which should motivate further experimental investigations." (PMID 36342924, 2022).
Right ventricular cardiomyopathy (1 paper, 2016). Right ventricular dysfunction (global or regional) with functional and morphological right ventricular abnormalities, with or without left ventricular disease. "Also of interest is the plakophilin 2 gene (PKP2), associated with right ventricular cardiomyopathy and multiple genes involved in mitochondrial energy metabolism (MTCH1, OXA1L, MUL1)." (PMID 27923400, 2016).
steatosis (1 paper, 2018). Increased lipid within the cytoplasm of cells. "More specifically, perturbation in endoplasmic reticulum and vesicles through the genes MUL1, TMEM135, OSBPL9, SCD1, SREBP-1C, GPAT3 can lead to steatosis." (PMID 30279702, 2018).
cancer (13 papers, 2015 to 2026). A tumor composed of atypical neoplastic, often pleomorphic cells that invade other tissues. "We focused our studies on Akt2 and HIF-1α coregulation by MUL1 since activation of these proteins is involved in metabolic phenotypes that favors glycolysis, a hallmark of cancer cells referred to as the Warburg effect." (PMID 35846359, 2022). "Furthermore, studies in ovarian cancer have indeed associated MUL1 induction by metformin with decreased Akt levels and cancer suppression." (PMID 38139010, 2023). "Similar to CPT2, MUL1 acts as an oncogene and as a tumor suppressor in different cancer types depending on the different targets." (PMID 40592838, 2025). "MUL1 is a mitochondrial membrane- located RING E3 ligase that has been linked to several pathologies, such as cardiovascular, neurological diseases and cancer, and thus been proposed as a potential therapeutic target." (PMID 40592838, 2025). "This review will highlight the different roles of MARCH5, RNF185 and MUL1 in cancer, focusing on their functions as potential oncogenes or tumor suppressors and defining a possible use for therapy." (PMID 38139010, 2023). "Given its role in the ubiquitination and proteolysis of AKT, MUL1 is often downregulated in different types of cancer." (PMID 36672167, 2023). "A similar mechanism has been demonstrated in ovarian cancer cells where MUL1 expression is induced by the anti-cancer agent Metformin." (PMID 36672167, 2023). "This makes MUL1 an interesting target for a therapeutic strategy aimed at reducing the levels of Akt (and especially Akt2) in cancers that overexpress it such as breast, lung and colon cancer." (PMID 38139010, 2023). "In this study, we showed that NTP and LTP, a liquid type of NTP, have anti-cancer effect through MUL1-induced AKT degradation in vitro." (PMID 26450902, 2015). "Since metabolic alteration can be exploited by cancer cells in order to achieve survival and progression, MUL1 levels in cancer could be predictive of a possible metabolic switch." (PMID 38139010, 2023). "Treatment with cisplatin (CDDP) increases MUL1 transcription in these cancer tissues." (PMID 36672167, 2023). "In the context of cancer, MUL1 can act both as an oncogene and as a tumor suppressor." (PMID 38139010, 2023). "On the other hand, MUL1 has a tumor suppressor role in other types of cancers." (PMID 38139010, 2023). "MUL1 may act as a tumor suppressor protein in some cancers however, MUL1 regulating signal pathways remain unclear." (PMID 29299162, 2017). "Thus, we manufactured a liquid type of NTP (LTP) and validated NTP anti-cancer effects through MUL1-mediated AKT ubiquitination in HNC cells." (PMID 26450902, 2015). "In addition, a therapy aimed at restoring the levels of MUL1 in those cancers may downregulate Akt2 and HIF-1α and achieve tumor regression, as seen in other models." (PMID 38139010, 2023). "Furthermore, our data indicate that the metabolic phenotype of MUL1(−/−) cells is distinct from the glycolytic state observed in cancer cells (Warburg effect), where increased pyruvate dehydrogenase (PDH) and lactate dehydrogenase (LDH) switch OXPHOS to glycolysis." (PMID 35846359, 2022). "In syngeneic and xenograft in vivo tumor models, LTP inhibited tumor progression by increasing the MUL1 level and reducing p-AKT levels, indicating that LTP also has an anti-cancer effect through the same mechanism as that of NTP." (PMID 26450902, 2015). "Herein, for the first time, we investigated the novel anti-cancer mechanisms of NTP through AKT ubiquitination and degradation through MUL1 E3 ligase in HNCs in vitro and in vivo." (PMID 26450902, 2015). "Additionally, it has been reported that MUL1 levels are regulated by the transcription factor FOXO3, another member of FOXO family, in cancer cells and primary myotubes." (PMID 37051468, 2023).
cancer (continued). "To assess the expression of Gp78 in multiple cancers, we used GEPIA-2 analysis to probe TCGA RNAseq data for mRNA expression of Gp78 and other ubiquitin ligases that induce mitophagy (PARK2, RNF185, MUL1, MARCH5, HUWE1, SIAH1) as well as the hypoxia-induced mitophagy proteins BNIP and NIX." (PMID 36284011, 2022). "Previously, we reported that MUL1 is suppressed in HNC and contributes to cancer development." (PMID 29299162, 2017). "However, when considering the mito E3s, inhibition of the proteasome could represent a valid strategy only in those cancers where MARCH5, RNF185 and MUL1 are upregulated, with the objective to stop their excessive activity." (PMID 38139010, 2023).
tumor (9 papers, 2015 to 2025). "In summary, our study provides a molecular basis for SLC44A2 as a potential tumor suppressor in CRC by downregulating CPT2-mediated mitochondrial FAO in a MUL1-dependent manner (Graphical abstract, generated using the Microsoft PowerPoint software)." (PMID 40592838, 2025). "In view of our findings indicating the activation of STAT3 signaling pathway through the degradation of SUZ12 and EZH2 mediated by SUMOylated HSPA9, we investigated the role of STAT3 in MUL1-induced tumor inhibition effects." (PMID 39113711, 2024). "Based on the reviewed literature, MARCH5 has mostly an oncogenic role, RNF185 acts as a tumor suppressor, whereas MUL1 can have both roles depending on the cell type." (PMID 38139010, 2023). "In both models, tumor volume and tumor weight were significantly reduced, and mitochondrial E3 ubiquitin protein ligase 1 (MUL1) was thought to be involved in this process." (PMID 34829929, 2021). "Our results indicate that SLC44A2 acts as a tumor suppressor in CRC by downregulating CPT2-mediated mitochondrial fatty acid oxidation via increasing the interaction between MUL1 and CPT2, supporting SLC44A2 as a potential therapeutic target in the treatment of this malignancy." (PMID 40592838, 2025). "However, by inducing the translocation of mitochondrial HSPA9 to the nucleus, MUL1-induced SUMOylation of HSPA9 played a tumor suppressive role in BCa cells." (PMID 39113711, 2024). "Tumor growth and GRP78 expression were inhibited after MUL1 cancer cell was knocked out, suggesting that the MUL1–GRP78 axis will become a new strategy for the treatment of head and neck cancer." (PMID 32850882, 2020). "Here we show that MUL1-mediated downregulation of CPT2 play a crucial suppressive role in CRC progression, suggesting that MUL1 may function as a potential tumor suppressor in CRC, which still needs more investigations." (PMID 40592838, 2025). "Consistent with this, analysis using the UALCAN database showed no significant change in MUL1 protein expression in CRC tumor tissues compared to normal tissues." (PMID 40592838, 2025).
infection (5 papers, 2017 to 2025). The state of being infected such as from the introduction of a foreign agent such as serum, vaccine, antigenic substance or organism. "RNAi targeting mul-1 and gpdh-1 resulted in enhanced resistance to pathogen infection, and RNAi for let-653 resulted in enhanced susceptibility to pathogen infection." (PMID 32127446, 2020). "Here, we found that inhibition by RNA interference (RNAi) or deletion by CRISPR/Cas9 of mul-1 enhances C. elegans resistance to infection by P. aeruginosa or Salmonella enterica." (PMID 32127446, 2020). "The regulation of mul-1 by various immune signaling pathways suggests that it is an innate immune factor, involved in a variety of responses to pathogen infection and host damage." (PMID 32127446, 2020). "In summary, we have identified the host mucin, MUL-1, in C. elegans as an innate immune factor that is exploited by P. aeruginosa during infection." (PMID 32127446, 2020). "Expression of mul-1 is upregulated upon infection with P. aeruginosa at 4 and 8 h, which would suggest that mul-1 is an immune response factor that is turned on to combat pathogen infection." (PMID 32127446, 2020). "In contrast to this suggested role and the typical role of mucins as immune effectors, our results indicate that certain pathogens use MUL-1 to tip the balance in their favor during infection." (PMID 32127446, 2020). "mul-1 and drd-50 are induced during infection with multiple bacterial pathogens, including P. aeruginosa." (PMID 30668573, 2019).
neurodegenerative disease (3 papers, 2019 to 2025). A disorder of the central nervous system characterized by gradual and progressive loss of neural tissue and neurologic function. "This Mul1–Mfn2 pathway is particularly relevant to neurodegenerative diseases associated with chronic mitochondrial dysfunction and altered ER-Mito interplay." (PMID 31409786, 2019).
neurological diseases (2 papers, 2023 to 2025). "Overall, MUL1 dysregulations can impact several pathologies, such as inflammatory, cardiovascular and neurological diseases; MUL1 has been proposed as a potential therapeutic target, concerning especially the mitochondrial derangements that may occur during these diseases." (PMID 38139010, 2023).
cardiac disease (1 paper, 2025). "This comprehensive analysis provides compelling evidence that E2 prevents cardiomyocyte hypertrophy by regulating MUL1, shedding light on a promising therapeutic target for cardiac diseases." (PMID 39971924, 2025). "Given the importance of estrogens in the onset of cardiac disease and their role in MUL1 regulation, as described in our previous results, we conducted these measurements in male and female mice at 37 weeks of age." (PMID 39971924, 2025). "MUL1 also mediates lipotoxicity-induced mitochondrial fission in hypertrophic models, underscoring its role in cardiac disease mechanisms." (PMID 39971924, 2025). "This highlights MUL1 as a promising target for therapeutic interventions in cardiac diseases." (PMID 39971924, 2025).
MUL1 also shares sentences with these, for which no sentence is quoted: Parkinson (2 papers); abortion (1); Alzheimer disease (1); amyotrophic lateral sclerosis (1); atherosclerosis (1); bacterial infection (1); bladder cancer (1); dysplasia (1); gastric cancer (1); heart failure (1); hemorrhage (1); hypertrophy (1); inflammatory bowel disease (1); intervertebral disc degeneration (1); ischemia (1); lung adenocarcinoma (1); memory impairment (1); metabolic disease (1); muscular dystrophies (1); myeloproliferative neoplasm (1); myocardial ischemia (1); myopathy (1); osteosarcoma (1); ovarian carcinoma (1); rhabdomyosarcoma (1); Stroke (1).